BGLT3 (beta globin locus transcript 3)
Synonyms: LINC01083; BGL3; lncRNA-BGL3
Gene: Long non-coding RNA gene on chromosome 11 (5,244,554 to 5,245,546, reverse strand). Ensembl gene ENSG00000260629.
Diseases named in the same sentence as BGLT3 in open-access papers:
BGLT3 is named in the same sentence as 11 diseases in open-access papers, as found by Europe PMC text mining. Sharing a sentence is not in itself a finding about the gene and the disease. The quoted sentences say what the papers report.
thyroid (1 paper, 2026). "In the early phases of thyroid oncogenesis, BRAF p.V600E or RET/PTC oncogenes drive the expression of HIF1α, although the concomitant overexpression of c-MYC, belonging to the same signaling pathway, quickly overturns HIF1α regulation by suppressing BGLT3 transcription at its locus." (PMID 41489907, 2026). "However, presenting OTUD3 to PTEN is not the sole relevant function of BGLT3 in thyroid carcinogenesis as this lncRNA is also involved in DNA repair." (PMID 41489907, 2026).
tumor (6 papers, 2014 to 2026). "Silencing of Bcr-Abl provokes a downregulation of these lncRNAs; among them, beta globin locus transcript 3 (non-protein coding) (lncRNA-BGL3) acts as a tumor suppressor transcript acting as a ceRNA for those miRNAs that target the oncosuppressor PTEN, such as miR-17, miR-20 and miR-106." (PMID 25428918, 2014).
BGLT3 also shares sentences with these, for which no sentence is quoted: chronic myeloid leukemia (3 papers); bladder cancer (1); cancer (1); glioma (1); leukemia (1); lung adenocarcinoma (1); osteosarcoma (1); papillary thyroid carcinoma (1); tongue squamous cell carcinoma (1).